IFNG (interferon gamma)
Diseases named in the same sentence as IFNG in open-access papers (continued):
Sharing a sentence is not in itself a finding about the gene and the disease.
melanoma (continued). "In contrast, a later study with melanoma cells found that IFNγ upregulated p21 and p27, which were not responsible for cell cycle inhibition." (PMID 37803324, 2023). "However, in the tumor microenvironment (TME) of melanoma, after identifying an abnormal antigen in major histocompatibility complex (MHC), T cells release interferon-gamma (IFN-γ) to improve tumour-killing efficiency." (PMID 37221594, 2023). "The mRNA level of ARNTL, AURKA, and IFNG in melanoma tissues were significantly higher than those in adjacent normal tissues." (PMID 35692844, 2022). "Based on the importance of tumor MHC-I expression and intact IFNγ signaling for clinical response to single agent anti-PD1 immunotherapy, we designed a rational workflow to generate a transplantable mouse melanoma model responsive to PD1 blockade." (PMID 36230753, 2022). "In C57BL/6J mice, N. caninum infection was found to induce significant macrophage recruitment to the infection site and increase secretion of interleukin 6 (IL-6), IL-12p40, and interferon gamma (IFN-γ), which was similar to the host immune responses against melanoma." (PMID 36138417, 2022). "In addition, CrPVIRES-ssRNA treatment markedly increased the frequency of antigen-specific CD8 T cells and interferon-gamma (IFN-γ) producing cells, which promoted immune responses and reduced tumor burden in melanoma-bearing mice." (PMID 36199130, 2022). "It was shown that IFN signaling is a target of EZH2 suppression in cancer: EZH2 represses IFNγ target genes in prostate, colorectal, and melanoma cancer cells, while pharmacological inhibition of EZH2 in melanoma results in the upregulated profile of IFNγ and IFN-α downstream targets." (PMID 36463299, 2022). "Indeed, increased immunoproteasome expression has been attributed to IFNγ secretion by tumor-infiltrating CD8+ T cells in several tumor types, including melanoma, colorectal cancer, gastric cancer, and breast cancer." (PMID 35936007, 2022). "JQ1 was characterized by induction of inhibitory relationship linking regulators of inflammation (IFNG, IL17A, TGFB2), melanoma biological behavior (EGFR, WNT3A, TEADs, MRTFB), cell-cell interaction (CD44, CCN2), YAP pathway (LLGL2, NSUN6) and main transcriptional regulators (FOS, JUN, FOXM1)." (PMID 36397155, 2022). "IFNγ could upregulate the expression of MHC-II on B16 cells, which augmented CD4+ T cell-mediated killing of melanoma." (PMID 36733396, 2022). "Recently, the overexpression of TNF, IFNG and IL2, among other molecules, have been reported as key molecules that may enhance melanoma progression through activating the JAK–STAT signaling pathway." (PMID 36289681, 2022). "Indeed, systemic administration of IFNγ increased levels of CXCL10 and intratumoral T cell infiltration in a phase 0 clinical trial for sarcoma, and intratumoral injection of IFNγ increased tumor CXCL10 and CXCL11 in melanoma patients." (PMID 33603130, 2022). "This bowel injury allowed the recruitment, activation, and mobilization of CCR7-expressing dendritic cells to Peyer patches, mLN, and tdLN, culminating in the massive infiltration of IFNγ-producing CD4+ and CD8+ TILs and tumor control of poorly immunogenic melanoma." (PMID 33262469, 2021). "We confirmed this observation and found that BLM treatment enhanced the number of tumor-infiltrating IFNγ-expressing CD8+ T cells in B16-F10 melanoma-bearing mice (data not shown)." (PMID 34378880, 2021). "This transfection was indispensable since melanoma cells lose expression of PD-L1 after in vitro culture without IFNγ—that is, the main inducer of its expression on tumor cells." (PMID 33809167, 2021). "Furthermore, TCGA melanoma samples show a significant positive correlation between NAMPT and IFNG expression, and more broadly between NAMPT levels relative to the GSEA Hallmark IFNγ response gene set." (PMID 33976173, 2021).
melanoma (continued). "The transfection of T cells, isolated either from PBLs or tumor-infiltrating lymphocytes (TILs), with caTLR4 mRNA, caCD40 mRNA, or both, enhanced the production of IFNγ and TNFα, upregulated 4-1BB and CD25, and increased the cytolytic activity against autologous melanoma cells in vitro." (PMID 33858437, 2021). "Furthermore, we analyzed the expression of TAPBPL on cancer cells following IFNγ stimulation in vitro and found that the expression levels of TAPBPL on neuro‐2a neuroblastoma and B16F10 melanoma were upregulated upon stimulation (Fig EV1G and H)." (PMID 33938620, 2021). "IL2RA, IL2R, IFNG, and IL7R were also significantly upregulated in melanoma tissues relative to normal tissues, and had a critically positive correlation to unfavorable prognosis in melanoma." (PMID 34159752, 2021). "In turn, IFNγ was mandatory to up-regulate MHC-I molecules expression and endogenous antigen presentation on melanoma cells, which allowed their recognition and elimination by cytotoxic T cells possibly through both perforin/granzyme- and Fas-mediated pathways." (PMID 34712615, 2021). "Interestingly, elimination of 3′-UTR AREs from IFNG gene (ARE-Del) decoupled IFN- production from post-transcriptional modifications, precipitating IFN-γ production and delayed tumor growth in a melanoma mouse model." (PMID 34446084, 2021). "We found that IFNβ strongly upregulated the levels of both Gal-9 protein and mRNA in A375 human melanoma cells, whereas IFNγ only moderately induced Gal-9 and TNFα did not have a detectable effect." (PMID 33547304, 2021). "In addition, FTO knockouts make melanoma cells sensitive to interferon gamma (IFN γ), thereby increasing the sensitivity of mouse melanomas to PD-1 monoclonal antibody treatment." (PMID 33926508, 2021). "Indeed, in biopsies of melanoma patients, colocalization of PD-L1 expressing tumor cells, CD8+ TILs and IFNγ, has been observed, and heterogenous expression of PD‐L1 was related to the T-cell infiltrate." (PMID 33809167, 2021). "In an inflammatory microenvironment, MHC II molecules can be aberrantly expressed by non-hematopoietic cells, including melanoma cells, which, similar to PD-L1 expression in melanoma, can occur following secretion of IFNγ by NK cells and cytotoxic T cells." (PMID 33842341, 2021). "Measurements of anti-tumor reactivity vary depending on the cancer (melanoma, uveal melanoma, lung, bladder), the method for determining tumor infiltrating lymphocyte (TIL) reactivity (IFNγ production, CD137/4-1BB and CD134/OX40 expression), and the types of cells that are tested." (PMID 32867034, 2020). "We quantitated IFNγ that was produced by ex vivo primed Pmel-1 CD8+ T cells on co-culture with melanoma cells that did not express gp100 at baseline but up-regulated gp100 on treatment with compounds." (PMID 32231230, 2020). "Analysis of reactivity against only TCLs/TCLs + IFNγ confirmed this pattern, except differences in non-melanoma (non-MM) tumors were no longer present (n = 143)." (PMID 33198174, 2020). "A study investigating IFNγ-mediated PD-L1 upregulation in multiple cancers including melanoma, renal cell carcinoma, head and neck cancer, and NSCLC, found that IFNγ was able to induce mRNA and protein PD-L1 expression by tumor cells regardless of constitutive PD-L1 expression." (PMID 33193345, 2020). "Clinically, these findings were confirmed in patients with advanced melanoma treated with domatinostat for 14 days, who demonstrated elevated expression of APM and MHC genes, the IFNG gene, and the IFN-γ and pembrolizumab response signatures in individual tumor samples." (PMID 31703604, 2019). "For melanoma tumour cells, CD107a activity was completely restored in the absence of platelet releasate, while IFNγ was unaffected." (PMID 30908480, 2019). "However, in patients with melanoma, a reverse in tumor-induced T cell exhaustion/dysfunction was achieved via dual blockade of TIM-3 and PD-1, which restored T cell secretion of IFNγ and TNFα." (PMID 30917934, 2019).
melanoma (continued). "To verify that the up-regulation of PD-L1 in tumor cells is a direct effect of the IFNγ present in the TME, we treated SM1 melanoma cells in vitro with NextA or vehicle control and then co-cultured with CD3/CD28 activated splenocytes in the presence of anti-PD1 antibody." (PMID 30992475, 2019). "As control, the release of TNFα, IL-6, and IFNγ was also determined for the untreated melanoma cells alone (data not shown)." (PMID 31192129, 2019). "Treatment of melanoma or renal cancer tumor cells with Nucl-TAP led to the activation of lentiviral transduced CD8+ T cells expressing the TCR specific to LRPAP1 peptide as measured by the acquisition of cytotoxic and IFNγ-secreting effector functions." (PMID 31434881, 2019). "Incomplete responses to IFNγ-stimulation, usually manifested as lack of induction of one or more markers were evident in 26 of 39 (67%) melanoma cell lines." (PMID 29977240, 2018). "We also examined the potential influence of melanoma driver oncogenes on IFNγ signaling activity and found that uveal melanoma (UVM) cells show evidence of diminished IFNγ pathway activity with minimal baseline and IFNγ induction of HLA-DR, NGFR, and PD-L2." (PMID 29977240, 2018). "It is worth noting that 5/7 melanoma cell lines with no IFNγ-mediated PD-L1 induction also showed no cell cycle profile changes in response to IFNγ treatment." (PMID 29977240, 2018). "Interferon-gamma was used in clinical trials for melanoma but no significant improvement for patients was observed." (PMID 29780381, 2018). "Re-stimulation of TILs from a MICA overexpressing human melanoma through their TCR showed that they have a reduced capacity to produce IFNγ compared to TILs derived from melanoma that did not express NKG2D ligands." (PMID 29568297, 2018). "TIL cocultured with adhered melanoma cells secreted similar or higher IFNγ levels per T cell than TILs that were cocultured with non-adherent melanoma cells, which were added simultaneously with TIL (p ≤ 0.05 at 8:1 and p = 0.06 at 1:1)." (PMID 29067023, 2017). "T cell reactivity measured by IFNγ secretion was detectable at all E:T ratios and specific, as HLA-mismatched melanoma did not induce cytokine secretion." (PMID 29067023, 2017). "Our data demonstrated a profound difference in the way in which immunogenic T-lymphocyte epitopes are presented by melanoma cells under IFNγ inflammatory versus non-inflammatory conditions." (PMID 26885372, 2016). "Other agents have been investigated in conjunction with melphalan, including tumor necrosis factor-alpha (TNF-α), interferon-gamma (IFN-γ), actinomycin D, and ADH-1, which is a cyclic pentapeptide, that inhibits N cadherin expression important in melanoma cell adhesion and migration." (PMID 26140669, 2015). "Syngeneic mice received subcutaneous administration of B16 melanoma, 4 T1 mammary carcinoma, and Lewis Lung Carcinoma (LLC), followed by administration of control saline, control placental endothelial cells, and interferon gamma primed endothelial cells (ValloVaxTM)." (PMID 25889119, 2015). "No significant changes in anti-melanoma immunity were observed in peripheral T cells by interferon-gamma ELIPSOT, or immunoglobulins by serum Western blotting." (PMID 26143264, 2015). "Many murine tumors (with the notable exception of B16 melanoma) express IDO1 upon exposure to IFNγ, but none of them expresses IDO1 in the absence of IFNγ." (PMID 25691885, 2015). "Our data indicate potential of non-virally modified IFNγ-expressing ADSCs for treatment of melanoma through direct effects of IFNγ." (PMID 25428727, 2014). "Actually, CD8+ T cells and IFNγ may induce the expression of indoleamine-2,3-dioxygenase (IDO) and PD-L1 in the melanoma tumor microenvironment, and inhibit the activation of additional T cells trafficking." (PMID 25428727, 2014).
melanoma (continued). "Detection of IFNγ in the melanoma lung tumor samples confirmed prolonged expression of IFNγ by IFNγ-ADSCs, most of which homed to the melanoma lung metastases and not to normal lung tissue." (PMID 25428727, 2014). "However, when DCs loaded with MAGE-AX were used, there has been increase in survival, a reduction of tumor size in mice with melanoma, and development of a specific immune response dependent on CD8 T cells and IFNγ production." (PMID 25759825, 2014). "Accordingly, DCIL-15 (not rIL-15)-based DNA vaccines elicited durable melanoma (TRP2)-specific IFNγ-producing CD8+ T cell responses." (PMID 25941586, 2014). "It was also not possible to measure secretion of interferon-gamma (IFN-γ) after coculture for 24 hours with these melanoma cells." (PMID 22364226, 2012). "No IFNγ production was seen when TIL were cultured in the absence of the autologous melanoma cell line." (PMID 21575188, 2011). "A follow up phase I/II study was performed with IDD-3 formulated by pulsing with 3 melanoma cell lines (M44, SKMel28, Colo829), with or without maturation with a bacterial membrane fragment of Klebsiella pneumoniae known as FMKp and interferon gamma (IFN-γ)." (PMID 20875102, 2010). "Sunitinib or Sorafenib activates the IFNγ/STAT1 pathway, which improve the expression of MHC I. When combined with whole-tumor-antigen-loaded nanovaccines, these nanovesicle formulations elicited a synergistic antitumor effect in both breast cancer and melanoma mouse models." (PMID 41019037, 2025). "Finally, we analyzed scRNA-seq data from two melanoma patients and specifically investigated whether combined HH/GLI and IFNγ/STAT1 signaling would affect the relative amount of IDO1 positive tumor cells." (PMID 39962447, 2025). "Our findings of impaired NK cell degranulation and IFNγ production in STS patients align with previous studies in other malignancies, such as acute myeloid leukemia and various solid tumors, but contrast with observations in melanoma patients, where degranulation is often preserved." (PMID 40805205, 2025). "In addition, we found that HDAC6i repressed IFNγ-mediated upregulation of CD47 in mouse and human melanoma cell lines through an unknown mechanism." (PMID 38414061, 2024). "Observing increased IFNγ-induced PD-L1 expression in the dedifferentiated 624Mel cells is partly in line with previous studies where SOX10 knockdown, which reduces MITF expression in melanoma cells, led to increased IFNγ-induced PD-L1 expression in three out of four tested melanoma cell lines." (PMID 39736644, 2024). "Further, we also observed single gene expression of MHC-I, MHC-II, interferon gamma signaling, Tumor/T-cell interaction, inflammation and cytotoxicity genes, all generally at higher levels in CTLA4res melanomas, albeit not always crossing significance thresholds." (PMID 38594286, 2024). "Moreover, the mRNA expressions of two critical XBP1 target genes ERDJ4 and EDEM1 were also significantly correlated with PTPRC, CD8A and IFNG, respectively, indicating the potential facilitative role of IRE1α-dependent UPR branch in anti-tumor immunity in melanoma." (PMID 38291473, 2024). "To determine whether this augmented IFNγ production could contribute to the superior killing activity of MCJ KO OT-I CD8 cells, we assessed B16-OVA melanoma cell killing in the presence or absence of an anti-IFNγ blocking Ab." (PMID 38789421, 2024). "Furthermore, the results suggest that a subgroup of dedifferentiated melanoma cells expresses increased levels of PD-L1, CCL2 and IL-8 in response to IFNγ, with IRF1 expression contributing highly to the upregulated inflammatory signaling responses of PD-L1high expressing cells." (PMID 39736644, 2024).
melanoma (continued). "IFNγ/FK866 combination-treated melanoma cells had the highest proportion of CTV-high (non-proliferating) cells and the lowest proportion of CTV-low (proliferating) cells, suggesting that IFNγ with FK866 decreased growth more significantly than either treatment alone." (PMID 36900204, 2023). "Also, while we demonstrated that the IFNγ-ERK cell death pathway is functional in a majority of the tested human melanoma lines, we did not investigate each line in detail." (PMID 37803324, 2023). "Our data suggest that microenvironmental GPR68 is required for melanoma tumor growth in males but dispensable in females, could be due to inhibition of infiltrating CD8+ T cells and NK cells as well as suppression of secretion of IFNγ by those two populations." (PMID 37350933, 2023). "In KMeC melanomas, IFNγ did not significantly upregulate caspase-3 expression, which was correlated with KMeC cytotoxicity, suggesting that there may be factors that affect caspase-3 expression as a characteristic of KMeC." (PMID 37022566, 2023). "Ectopic expression of Cas9 and single guide RNAs (sgRNAs) targeting KAT8 in multiple cell lines (osteosarcoma cell line 143B, malignant melanoma cell line A375 and lung cancer cell line A549) significantly decreased the total protein and mRNA levels of PD-L1 with or without IFNγ exposure." (PMID 36894639, 2023). "A similar result was obtained in urothelial, melanoma, and non-small cell lung carcinoma in which IFN-γ signaling-related genes, including IFNG, CD274, LAG3, and CXCL9, could well predict about who could benefit from the immunotherapy via anti-PD-L1/PD-1 antibody." (PMID 37637034, 2023). "This provides evidence that IFNγ is involved in a negative feedback loop in melanoma to limit anti-tumor immunity by restricting stem-like T cell longevity, offering new strategies to enhance stem-like T cell potential in tumors and potentially improve adoptive T cell transfer therapies." (PMID 36658158, 2023). "Furthermore, our findings may be particularly relevant to IFNγ-rich tumors and MITF-expressing melanomas." (PMID 36812891, 2023). "Pre-treatment of the NF-1LOF melanoma cell line MeWo and the BRAFMut MaMel51 with the RSK inhibitor PMD-026 could significantly enhance the activation of both gp100- and Melan-A-specific T cells as quantified by an increased IFNγ secretion." (PMID 37464364, 2023). "Importantly, enhanced IFNγ production and improved target cell killing by PD-1high CAR T cells was observed in human anti-IL-13 receptor α2 (IL13Rα2) CAR-T cells co-incubated with a human melanoma cell." (PMID 37388744, 2023). "Release of exosomes from melanoma cells also constitutes a rapid tumor cell response to CTL attack; exosomes contain an array of different molecules that may modulate the activity of CTLs including PD-L1, which increases in exosomes upon exposure to IFNγ." (PMID 35592329, 2022). "Additionally, they demonstrated that melanoma cells were able to reduce IFNγ secretion by this subset while TNFα was not affected, which is in contrast with the TNFα up-regulation we observed." (PMID 35173725, 2022). "Consistently, a correlation matrix profiling of gene mRNA expression in TCGA collection of melanoma tumors showed that CD40 expression significantly and positively correlates with CD4 and CD8 infiltrates, as well as with type 1 cytokine responses based on IFNγ and GzmB expression patterns." (PMID 34092233, 2021). "However, our study clearly expands on this concept and is unique in that it examines the metabolic roles of Nampt induction directly by IFNγ-dependent Stat1 recruitment to NRE1 and the effects of this phenomenon in the context of the immune cells in the TME, including melanoma patients." (PMID 33976173, 2021).